MGMT (O-6-methylguanine-DNA methyltransferase)
Diseases named in the same sentence as MGMT in open-access papers (continued):
Sharing a sentence is not in itself a finding about the gene and the disease.
glioma (continued). "Additionally, there is no clinically approved glioma-specific NGS panel, and none of the developed panels could identify MGMT-promoter methylation relevant for predicting temozolomide responsiveness." (PMID 37908227, 2023). "While CELF2 expression is a marker of good prognosis in low-grade glioma, we found conversely that CELF2 had no prognostic value in GBMs, with the exception of classical non-methylated subtypes on the promoter of MGMT, where high CELF2 expression was of poor prognosis." (PMID 37894405, 2023). "Patients with glioma were divided into different groups based on different clinical characteristics for age (age<42, age≥42), gender (female, male), grade (WHO 2, WHO 3, and WHO 4), IDH (mutant, wild type), 1p19q (codel, non-codel), and MGMT (methylated, un-methylated) status." (PMID 35812432, 2022). "Moreover, BCAT1 is an independent prognostic factor for glioma patients, high BCAT1 expression is related to unfavorable clinical parameters including older age, IDH wildtype, no 1p/19q codeletion, ATRX wildtype and MGMT unmethylated." (PMID 33493139, 2021). "Similarly, glioma patients with MGMT promoter-methylated tumours had a significantly longer PFS (18 vs. 7 months) and OS (29 vs. 12 months) than glioma patients whose tumours lacked MGMT promoter methylation (both P < 0.001)." (PMID 32034446, 2020). "Since the MGMT promoter methylation status has been proven to be an independent prognostic and predictive marker in glioma regardless of the WHO classification or chemotherapy regimen, prediction of the MGMT promoter methylation status using 18F-FDG-PET radiomics may have great clinical potential." (PMID 31426864, 2019). "In particular, high-grade gliomas are characterized by a large heterogeneity that affects treatment prognosis, and further studies are needed to clarify what advantage SDT might have for a better prognosis, e.g., for patients with MGMT-positive or -negative status." (PMID 40430146, 2025). "However, MGMT expression is not the sole determinant of TMZ sensitivity and IDH1 mutant and wild-type gliomas have different molecular ontogenies, making comparisons between IDH1 mutant and wild type gliomas uninformative as to which tumor characteristics can be attributed directly to IDH1 mutation." (PMID 28178660, 2017). "However, the value of MGMT methylation has not been tested in patients treated with PCV (Procarbazine, CCNU and Vincristine), a recognised effective regimen in the treatment of recurrent high grade glioma used as standard therapy prior to the introduction of temozolomide." (PMID 24952577, 2014).
astrocytoma (115 papers, 2004 to 2026). "Another important epigenetic marker associated with treatment and outcome in IDH-mutant astrocytoma is MGMT promoter methylation." (PMID 39012509, 2024). "Collectively, extent of MGMT promotor methylation was strongly associated with other molecular markers and added prognostic information in astrocytoma, IDH-wildtype." (PMID 33184319, 2020). "Samples of astrocytomas with MGMT promoter methylation had less TERT mutations than samples with low MGMT promoter methylation (p=0.041)." (PMID 29221210, 2017). "Differences in the prevalence of IDH mutation and MGMT promoter methylation between lower-grade astrocytomas and grade IV GBM were significant." (PMID 29221210, 2017). "Additionally, in one study, the MGMT methylation was also seen in nearly all IDH-mutated astrocytomas and oligodendrogliomas." (PMID 39767640, 2024). "Consequently, several clinical trials have illustrated that MGMT promoter methylation is associated with improved survival compared to unmethylated tumors and is an independent prognostic factor in high-grade astrocytoma." (PMID 36147920, 2022). "We find that the genome-wide GBM pattern of CNAs is statistically a better predictor of astrocytoma outcome, corresponding to greater median survival time difference, proportional hazard ratio, and concordance index, than MGMT promoter methylation and IDH1 mutation." (PMID 27798635, 2016). "Down regulation of MGMT transcript levels, via hypermethylation of the MGMT promoter, is associated with malignant progression of astrocytomas and is being used in the clinic to identify patients that may benefit the most from treatment with temozolomide." (PMID 20423517, 2010). "Moreover, MGMT unmethylation was associated with poor overall survival in astrocytoma." (PMID 38404571, 2024). "MGMT promoter methylation was more frequent in oligodendrogliomas IDH mutant 1p19q codeleted (80.8%) as compared to IDH-mutant astrocytomas (62.9%; p = 0.048)." (PMID 41341389, 2025). "Examination of the tissue specimen revealed an IDH-mutant astrocytoma CNS WHO grade 3 with an O-6 methylguanine-DNA methyltransferase (MGMT) promotor methylation level of 5.5%." (PMID 39949738, 2025). "MGMT Promoter Methylation is associated with better OS and PFS for IDH mutant grade 4 astrocytoma only." (PMID 40949165, 2025). "Almost 70% of IDH-mutant astrocytomas are known to harbor methylated MGMT promoters, making them more likely to respond to TMZ treatment." (PMID 40697380, 2025). "Limited data suggests a prognostic role of MGMT promoter methylation in IDH-wt astrocytomas with regard to chemotherapy response and OS." (PMID 41466163, 2025). "22% of astrocytomas and 7% of oligodendrogliomas, respectively, had an unmethylated MGMT promoter (p 0.0156, Fisher’s exact test)." (PMID 40849395, 2025). "A subsequent analysis of ADG subtypes revealed that patients with astrocytoma in the MGMT unmethylated group had a shorter OS than those in the MGMT methylated group." (PMID 38404571, 2024). "The relevance of MGMT methylation in IDH mutant astrocytomas and oligodendrogliomas presents a complex landscape." (PMID 39055560, 2024). "Given the hypermethylated phenotype of IDH-mutant astrocytomas, MGMT promoter hypermethylation is prevalent in IDH-mutant astrocytomas; however, it is said to have prognostic, as opposed to predictive, value." (PMID 38791984, 2024). "Despite this controversy, MGMT-promoter methylation is still considered a prognostic factor for patients with G4 astrocytoma." (PMID 38827324, 2024). "Unmethylated MGMT in astrocytomas and the overexpression of CD47 and TIGIT in ADG tissues are associated with a poor prognosis." (PMID 38404571, 2024).
astrocytoma (continued). "It would be of interest to investigate the association between older patients and increased odds of MGMT methylation, in IDH1 mutant astrocytomas." (PMID 39767640, 2024). "In summary, clinical management of both low‐grade and high‐grade paediatric/adult astrocytoma is governed by four key prognostic factors, age at diagnosis, MGMT methylation status, level of surgical intervention and use of chemotherapeutics such as TMZ." (PMID 38299304, 2024). "For pTERT mutation and MGMT methylation in astrocytoma and GBM, only the MGMT unmethylated group showed a shorter OS in astrocytomas (P < 0.0001)." (PMID 38404571, 2024). "To date, there is only limited data suggesting a prognostic role of MGMT promoter methylation in IDH 1/2 wt astrocytomas for chemotherapy response and overall survival." (PMID 38326661, 2024). "The diagnosis was in favor of astrocytoma IDH mutant (IDH1 R132H positive, ATRX mutation, KI67-MIB1 70%, MGMT promoter methylation 55.55%), WHO grade 4." (PMID 39335096, 2024). "During diagnosis, 14 patients had grade 4 astrocytoma, of which MGMT gene promoter was methylated in 5 patients out of 8 where it was available." (PMID 37109071, 2023). "Amongst IDH-mutant astrocytomas, MGMT promoter methylation is correlated with prolonged overall survival." (PMID 37239289, 2023). "The MGMT promotor was methylated in 19 primary astrocytomas and in three out of these, the MGMT promotor was unmethylated upon recurrence." (PMID 36739454, 2023). "The published literature has demonstrated that a well-selected cohort of patients like recurrent oligodendroglioma, IDH mutant astrocytoma, and MGMT gene promoter methylated GBM have better outcomes following salvage reirradiation." (PMID 37109071, 2023). "The group comprising of IDH-mutant WHO grade 4 astrocytomas frequently showed methylation of MGMT promoter (6/8; 75%)." (PMID 39760063, 2023). "Currently, molecular markers for clinical classification, prognosis, and therapeutic response prediction of astrocytoma include MGMT promoter methylation and homozygous CDKN2A and/or CDKN2B deletions." (PMID 37667984, 2023). "As expected, IDHmut astrocytomas with high scores by the methylation classifier (cutoff score = 0.955 by Cutoff Finder) were more likely to be MGMT promoter methylation-positive." (PMID 37919784, 2023). "In one case, a newly diagnosed grade 4 IDH-mutant astrocytoma was positive for MGMT promoter methylation on pyrosequencing (35.9% CpG site methylation), but the recurrent tumor 8 months later was negative on pyrosequencing (5.4%)." (PMID 37919784, 2023). "Stratification of intramedullary astrocytomas by MGMT methylation status can help assess prognosis and determine the value of adjuvant chemotherapy compared to resection and radiotherapy." (PMID 36147920, 2022). "Our data suggest that YAP1 should be further investigated as a potential druggable target in the sub-group of recurrent chemotherapy-treated MGMT unmethylated astrocytoma." (PMID 34771529, 2021). "We further observed the potential role of MGMT methylation in this study as YAP1 mRNA expression and codon 273 mutation were particularly prognostic in the MGMT unmethylated sub-group of astrocytoma patients treated with chemotherapy." (PMID 34771529, 2021). "Differentiating MGMT methylated astrocytomas early on is especially important for identifying tumor susceptibility to temozolomide chemotherapy treatment as well as predicting the efficacy of Carmustine wafer implantation." (PMID 33915813, 2021). "Among these, age, tumor grade and astrocytoma histology were associated with poor OS, DSS and PFI, while IDH mutation status, 1p/19q codeletion status, and MGMT promoter methylation status were associated with better OS, DSS, and PFI." (PMID 33425727, 2020).
astrocytoma (continued). "There is currently an ongoing clinical trial (NCT03011671) for the use of a CA inhibitor in the therapy of malignant astrocytoma (MGMT methylated grade III-IV astrocytomas)." (PMID 32610540, 2020). "• Radiomics using magnetic resonance imaging can preoperatively perform satisfactory prediction of MGMT methylation in grade II-IV astrocytomas." (PMID 30039219, 2019). "Oxygen 6-methylguanine-DNA methyltransferase (MGMT) promoter methylation is a significant prognostic biomarker in astrocytomas, especially for temozolomide (TMZ) chemotherapy." (PMID 30039219, 2019). "In this study, a preoperative and low-cost radiomics analysis was used to integrate imaging features from tumour and peritumoral oedema habitats on CE-T1-WI and T2-FLAIR images to predict MGMT promoter methylation in patients with grade II-IV astrocytoma." (PMID 30039219, 2019). "Accordingly, the average methylation levels of the MGMT promoter was significantly lower in astrocytomas IDHwt (14.3%) versus both astrocytomas IDHmt (24.1%; p = 0.030) and oligodendrogliomas (32.4%; p = 0.0001)." (PMID 31877896, 2019). "The proposed radiomics signature accurately predicted MGMT promoter methylation in patients with astrocytomas, and achieved survival stratification for TMZ chemotherapy, thus providing a preoperative basis for individualised treatment planning." (PMID 30039219, 2019). "Second row (panel β) presents a patient with a WHO III° astrocytoma (MGMT+, IDH1+, LOH1p/19q−) with an ambiguous report concluding that no high-grade recurrence was detected." (PMID 31601829, 2019). "In our study, MGMT promoter methylation status successfully stratified astrocytoma patients treated with adjuvant TMZ chemotherapy into two groups with significant prognostic differences, consistent with previous research." (PMID 30039219, 2019). "In our study we found 60.3% cases with MGMT methylated sequences as compared to 39.7% unmethylated DNA wherein GBM accounted for 53.1% with methylated DNA followed by Astrocytoma 64.2% and Oligidendrioglioma 85.7%." (PMID 29712977, 2018). "In IDH-WT astrocytomas, hypermethylation of the MGMT promoter is predictive of benefit deriving from treatment with temozolomide." (PMID 30279357, 2018). "Nearly all astrocytomas with IDH mutation were lower-grade astrocytomas, and the prevalence of MGMT promoter methylation in lower-grade astrocytomas was higher than that in GBM (p=0.032, Fisher's exact test)." (PMID 29221210, 2017). "To date, the only gene for which methylation of its promoter has been considered quite important in astrocytoma tumorigenesis is MGMT." (PMID 22389839, 2012). "The MGMT promoter region of the progressive low-grade astrocytoma (cases 1, 2 and 6), 1 secondary GB (case 9) and 5 primary GBs (cases 11, 13, 15, 17 and 18) were sensitive to digestion by both HpaII and MspI." (PMID 22264301, 2012). "Conversely, the low‐risk subtype, characterized by younger age, better prognosis, astrocytoma/oligodendroglioma, lower tumor grades, and favorable molecular profiles (IDH mutation, 1p19q codeletion, MGMT promoter methylation), indicated chemotherapy sensitivity." (PMID 40264576, 2025). "The evidence suggests that beyond GBM, colorectal cancer, small cell lung cancer, IDH mutant astrocytoma, and oligodendroglioma could benefit from a deeper understanding of MGMT methylation dynamics." (PMID 39055560, 2024). "In addition, levels of MGMT methylation in grade 2 astrocytoma tissue were higher than in grades 3 and 4 (P = 0.014)." (PMID 38404571, 2024). "The rate of MGMT methylation in astrocytoma was significantly higher than that in GBM (P < 0.0001)." (PMID 38404571, 2024).
astrocytoma (continued). "Among all adult-type diffuse gliomas combined, the optimal driver mutation VAF (either TERT for IDHwt GBM or IDH1/2 for IDHmut astrocytoma and IDHmut oligodendroglioma) in the context of MGMT promoter methylation pyrosequencing was determined by Cutoff Finder at 0.325." (PMID 37919784, 2023). "Among 445 samples assessed via pyrosequencing, 217 (49%) tested positive for MGMT promoter methylation (101 IDHwt GBMs, 68 IDHmut astrocytomas, 48 IDHmut oligodendrogliomas), while 228 (51%) tested negative (200 IDHwt GBMs, 25 IDHmut astrocytomas, 3 IDHmut oligodendrogliomas)." (PMID 37919784, 2023). "Furthermore, we identified sub-groups (codon 273 mutant and/or low YAP1 level) of MGMT unmethylated recurrent chemotherapy-treated astrocytoma that responded well to chemotherapy." (PMID 34771529, 2021). "In addition, MGMT was downregulated in all three major astrocytoma clusters in comparison to normal brain." (PMID 32604718, 2020). "The Mann-Whitney U-Test was used to analyze whether expression of analyzed genes were associated with patient gender, age at the time of surgery, malignancy grade of astrocytoma, IDH mutation and MGMT gene methylation status." (PMID 33036421, 2020). "In terms of astrocytoma, the updated classification allowed to classify astrocytoma tumors more accurately, as well as, to predict the outcome of patients, and to select treatment strategy, according to the MGMT methylation or IDH status." (PMID 33036421, 2020). "Quantification of MGMT promoter methylation may add prognostic information in patients with astrocytoma, IDH wild-type." (PMID 33184319, 2020). "Interestingly, PTEN deletion had poor prognostic value in astrocytomas IDH-wildtype (p = 0.015), while in GBM IDH-wildtype was associated with better overall survival (p = 0.042) as well as MGMT promoter methylation (p = 0.009)." (PMID 31623593, 2019). "Thus, there is an urgent need in clinical practice for preoperative and non-invasive prediction of MGMT promoter methylation in grade II-IV astrocytomas." (PMID 30039219, 2019). "MGMT could be studied in 48 astrocytoma cases, and alterations were found in all grades but in pilocytic astrocytomas." (PMID 22389839, 2012). "We could also detect one case of pediatric high-grade astrocytoma with MGMT hypermethylation, representing 17% of cases analyzed (6 cases)." (PMID 22389839, 2012). "However, methylation of some genes, like MGMT, has demonstrated to be critical, not only in tumorigenesis, but also in astrocytoma drug resistance." (PMID 22389839, 2012). "BLU, RASSF1A and MGMT genes hypermethylation in astrocytoma and neuroblastoma cell lines." (PMID 18298842, 2008). "BLU, RASSF1A and MGMT genes hypermethylation in astrocytoma tumor samples." (PMID 18298842, 2008). "There is no clear evidence on whether IDH mutation or MGMT promoter methylation can affect the anti-tumor activity of PRMT5 in G4 astrocytoma when used in conjunction with other chemotherapeutic agents." (PMID 38827324, 2024). "The recently published results of the NOA-08 trial on elderly malignant astrocytoma patients and the Nordic trial on elderly GBM patients showed that elderly malignant astrocytoma patients with methylated MGMT promoter may receive as much benefit from TMZ as from radiotherapy alone." (PMID 24420923, 2014). "In contrast to GB, IDH-mutant astrocytomas often harbor wild-type EGFR and PTEN genes, along with MGMT promoter methylation." (PMID 41426972, 2025). "As MGMT status was unavailable in 38% of HGG patients and 50% of IDH1-mutant astrocytomas, it was excluded from the primary model." (PMID 40261557, 2025). "A total of 70 patients (45 males, 25 females; mean age: 60 years) with histologically confirmed HGG (60 GBM and 10 astrocytoma WHO grade 4) and known MGMT promoter methylation status were included." (PMID 41476598, 2025).